CERS6 (ceramide synthase 6)
Diseases named in the same sentence as CERS6 in open-access papers (continued):
Sharing a sentence is not in itself a finding about the gene and the disease.
colitis (7 papers, 2017 to 2025). Inflammation of the colon. "Conversely, loss of CerS6 in splenocytes in a T cell transfer model of colitis, protected from disease." (PMID 38398179, 2024). "Germline loss of CerS5 or CerS6 exacerbates inflammation in a dextran sulfate sodium (DSS)-induced colitis mouse model." (PMID 36052066, 2022). "Different from the proinflammatory responses of CerS2 knockout in CD4+ T cells, transfer of CerS6-deficient CD4+ T cells induced less colitis compared to WT cells." (PMID 36052066, 2022). "The underlying reason for the enhanced colitis and/or neutrophil infiltration in CerS6-deficient mice will require further analysis." (PMID 29374263, 2018). "Pathology and the MPO functional assay suggested that DSS-induced colitis significantly increased the presence of neutrophils in the intestines of CerS6-deficient mice." (PMID 29374263, 2018). "In this study we analyzed how deficiency of CerS6 impacts on the development of colitis using an adoptive transfer model." (PMID 29138469, 2017). "Adoptive transfer of CerS6-deficient splenocytes, which have significantly decreased levels of C16-ceramide, showed that CerS6-deficiency protected against the development of colitis." (PMID 29138469, 2017). "As CerS6 mRNA is strongly expressed in cells of the immune system, we investigated how CerS6-deficiency impacts on the development of colitis in an adoptive transfer model." (PMID 29138469, 2017). "In addition, intestinal epithelial cells (IECs) isolated from fat-mass-and-obesity-associated protein (FTO) conditional knockout mice were more susceptible to DSS-induced colitis and demonstrated decreased CerS6 expression." (PMID 38398179, 2024). "Interestingly, CerS5 and CerS6 knockdown was shown to sensitize mice to azoxymethane/dextran sodium sulfate-induced colitis and increased cases of colitis-associated colon cancer." (PMID 34069611, 2021). "CerS6-ko mice are more susceptible for DSS-induced colitis than wild-type mice." (PMID 32630271, 2020). "Thus DSS-induced colitis resulted in similar weight loss and disease activity index by day 8 but progressed with different kinetics in wild type and CerS6-deficient mice." (PMID 29374263, 2018). "We therefore hypothesize that increased S1P in colon tissue of DSS treated CerS6-deficient mice is associated with colitis related inflammation." (PMID 29374263, 2018). "In this study we analyzed the effect of CerS6-deficiency on susceptibility to DSS-induced colitis." (PMID 29374263, 2018). "Our data suggest that protection from colitis following adoptive transfer of CerS6-deficient splenocytes maybe related to their ability to migrate and proliferate in vivo rather than subset development or cytokine expression." (PMID 29138469, 2017). "In inflammatory models, such as colitis and graft-vs-host disease (GVHD), CerS6-deficient T cells exhibit reduced inflammation, suggesting a protective effect." (PMID 40597360, 2025). "For example, CerS5 and CerS6 knockout mice show increased susceptibility to DSS-induced colitis and colitis-associated colon cancer." (PMID 40597360, 2025). "Similar to global knockout of CerS5, total body loss of CerS6 exacerbated colitis pathology scores and increased neutrophil infiltration in mice with DSS-induced colitis." (PMID 38398179, 2024). "Previously it has been shown that ceramide synthase 6 and 2 influence colitis in several animal models with sometimes opposite effects." (PMID 32630271, 2020). "While CerS6-deficient mice are protected from T cell mediated colitis, in the T cell independent DSS model lack of CerS6 resulted in a more rapid onset of disease symptoms." (PMID 29374263, 2018). "In this study we used ceramide synthase 6 (CerS6) deficient mice, which have a reduced ability to generate long chain C16-ceramide, to investigate the role of this enzyme in dextran sodium salt (DSS)-induced colitis." (PMID 29374263, 2018).
colitis (continued). "To determine whether CerS6 splenocytes differed in their ability to induce colitis, we isolated naïve CD4+CD45RBhi cells from either wild type or CerS6-deficient mice and adoptively transferred them into RAG1-deficient recipients." (PMID 29138469, 2017). "In contrast, pharmacological inhibition or genetic ablation of CerS6 impairs TCR signaling in response to alloantigens, leading to reduced T cell responses in GVHD and colitis." (PMID 40597360, 2025). "In CerS6-ko mice, higher sensitivity towards DSS-induced colitis has mainly been referred to an increase in neutrophil infiltration." (PMID 32630271, 2020). "In this study, we further elucidate the role of CerS6 in DSS-induced colitis, which is independent of T lymphocytes." (PMID 29374263, 2018). "Our study suggests that lack of CerS6 expression differentially impacts the development of colitis, depending on the model used." (PMID 29374263, 2018). "In conclusion, we have shown that CerS6-deficient mice are more susceptible to DSS-induced colitis, which contrasts with the protective effect that lack of CerS6 has in adoptive transfer models of colitis." (PMID 29374263, 2018).
leukemia (6 papers, 2015 to 2020). A malignant (clonal) hematologic disorder, involving hematopoietic stem cells and characterized by the presence of primitive or atypical myeloid or lymphoid cells in the bone marrow and the blood. "Another study reported that stichoposide D (STD) —a STC structural analog that contains glucose instead of quinovose in its carbohydrate chains—induces leukemia cell apoptosis through the activation of ceramide synthase 6 (CerS6)." (PMID 29416631, 2018). "Next, we compared CERS6 protein levels in 10 leukemia cell lines 31 to PBMCs and T lymphocytes isolated from blood of healthy human volunteers, representing normal cells." (PMID 30206207, 2018). "In contrast, STD induces apoptosis of leukemia cells and inhibits growth of leukemia xenografts through the activation of Fas/CerS6/p38 kinase." (PMID 27827870, 2016). "Activation of Fas, CerS6, and p38 kinase were observed in human primary leukemia cells, and these molecules were clustered in lipid rafts by STD." (PMID 26318294, 2015). "Finally, cladoloside C2 induced leukemia cell apoptosis by activating the Fas/CerS6/p38 kinase/JNK/caspase-8 pathway in lipid rafts." (PMID 29642569, 2018). "In contrast, STD induced leukemia cell apoptosis by activating ceramide synthase 6 (CerS6)." (PMID 29642569, 2018). "Here, we show that STD is able to enhance ceramide generation by up-regulating CerS6, and therefore modulate the phosphorylation of p38 kinase, leading to apoptosis in K562 cells, HL-60 cells, and human primary leukemia cells derived from patients with acute myeloid leukemia (AML)." (PMID 26318294, 2015). "Our results suggest that STD is a promising compound that may be useful in future novel anti-leukemia strategies by targeting multiple pathways along with ceramide generation through the activation of Fas and CerS6, leading to p38 kinase activation in lipid rafts." (PMID 26318294, 2015). "The role of Fas (CD95), ceramide synthase 6 (CerS6) and p38 kinase during STD-induced apoptosis was examined in human leukemia cells." (PMID 26318294, 2015).
gastric cancer (5 papers, 2020 to 2025). A primary or metastatic malignant neoplasm involving the stomach. "CerS6 overexpression has been described as a biomarker in gastric cancer, and CerS6 overexpression was associated with poor patient survival, invasion, and metastasis in gastric cancer." (PMID 34069611, 2021). "CERS6 has also been identified as an oncoprotein in gastric cancer that disrupts the SOCS2/JAK2/STAT3 pathway." (PMID 41203639, 2025). "CerS6 overexpression corelates with poor patient survival and CerS6 knockdown decreases proliferation, migration, and invasion of gastric cancer cells." (PMID 37760612, 2023).
Hyperglycemia (4 papers, 2017 to 2025). An increased concentration of glucose in the blood. "In humans, CERS6, the primary enzyme responsible for synthesizing C14–C16 ceramides, correlates with BMI, hyperglycemia, and decreased insulin sensitivity." (PMID 41278909, 2025). "BMI fat content and hyperglycemia positively correlated with CerS6 expression." (PMID 31496996, 2019).
non-small cell lung carcinoma (3 papers, 2018 to 2023). A group of at least three distinct histological types of lung cancer, including non-small cell squamous cell carcinoma, adenocarcinoma, and large cell carcinoma. "CERS6 is associated with metastasis and poor prognosis in non-small cell lung cancer (NSCLC) patients through d18:1/C16:0 ceramide (C16 ceramide)-mediated cell migration, though the detailed mechanism has not been elucidated." (PMID 37345118, 2023). "CERS6 is known to be associated with metastasis and poor prognosis in non-small cell lung cancer (NSCLC) patients because of C16 ceramide production, though the underlying mechanism remains largely unelucidated." (PMID 37345118, 2023). "In accord with those reports, we previously showed that CERS6 overexpression in non-small cell lung cancer (NSCLC) was associated with poor prognosis and distant lymph node metastasis." (PMID 37345118, 2023). "Pemetrexed/sildenafil (P/S) cotreatment also increased autophagy in non-small cell lung carcinoma (NSCLC) cells (A549) via an induction of CerS6 (ceramide synthase 6) expression and the disruption of HDAC6 content." (PMID 31861179, 2019). "In non-small cell lung cancer, CERS6 levels were markedly higher in comparison to controls and was found to be associated with poor prognosis and increased metastasis." (PMID 30206207, 2018).
pancreatic cancer (3 papers, 2018 to 2025). "As a result, inhibiting the AKT1/FOXP3/CERS6 axis can be a possible tactic to prevent the growth of pancreatic tumors." (PMID 38919615, 2024). "The tissues of pancreatic tumors have elevated expression of the Ceramide synthase (CerSs) isoform CERS6." (PMID 38919615, 2024). "To test whether changes in ceramide expression levels occur, we probed the ceramide de novo synthesis pathway by analyzing the expression of enzymes SPT, CERS-6, DEGS1 at 2, 4, and 6 hours after dosing with GT3, K-Ras mutated MIA PaCa-2 and Panc 1, and wild type BxPC3 pancreatic cancer cells." (PMID 29769046, 2018).
acute lymphoblastic leukemia (2 papers, 2018 to 2021). Leukemia with an acute onset, characterized by the presence of lymphoblasts in the bone marrow and the peripheral blood. "CERS6 and C16-Cer levels were significantly higher in acute lymphoblastic leukemia (ALL) cells in comparison to peripheral blood mononuclear cells and T lymphocytes derived from healthy human volunteers." (PMID 30206207, 2018).
colorectal cancer (2 papers, 2016 to 2023). A primary or metastatic malignant neoplasm that affects the colon or rectum. "First, significant differences in gene expression between normal tissue and colorectal cancer tissue were observed for ASAH1, ACER3, CERS2, and CERS6." (PMID 37758931, 2023).
COVID-19 (2 papers, 2021 to 2023). A disease caused by infection with severe acute respiratory syndrome coronavirus 2. "Since Cer(d18:1/16:0) and Cer(d18:1/24:1) are the predominant subclasses seen in the plasma samples of the COVID-19-infected group, focusing on modulation of CerS2 and CerS6 seems to be the logical therapeutic approach." (PMID 34675292, 2021). "However, no significant regulation was observed in the gene expression of CERS1, CERS3, CERS5, and CERS6 within the same COVID-19 group." (PMID 37566018, 2023).
hyperlipidaemia (2 papers, 2022 to 2025). "This study suggests that the decreased level of Cer in the serum is due to the reduced expression of its upstream CerS6 protein, indicating that CerS6 is involved in lipid metabolism in lipoprotein gene-KO animal models, which may improve hyperlipidaemia." (PMID 41154683, 2025). "Considering that the CerS6/PP2A/AKT pathway is involved in lipid regulation, this study offers new insights into the treatment of hyperlipidaemia." (PMID 41154683, 2025).
liver disease (2 papers, 2025). "Recent studies also found that CerS6 upregulation is associated with alcohol-associated liver disease and cardiovascular disease." (PMID 40057751, 2025).
lymph node metastasis (2 papers, 2020 to 2025). "Among the examined genes, the expression of CERS6 was significantly elevated in NSCLC and also shown to be associated with poor patient prognosis as well as lymph node metastasis." (PMID 32902157, 2020). "Next, we examined the relationship between CERS6 protein expression and other characteristics such as gender, age, TNM stage, pathological grade, and lymph node metastasis." (PMID 41203639, 2025).
multiple sclerosis (2 papers, 2017 to 2018). A progressive autoimmune disorder affecting the central nervous system resulting in demyelination. "In experimental autoimmune encephalomyelitis (EAE), an animal model of multiple sclerosis, CerS6-deficiency enhances inflammation through increased infiltration of neutrophils as CerS6 was not able to counteract CD11b mediated activation and CXCR2-mediated migration." (PMID 29138469, 2017). "Lack of CerS6 increases aggressiveness of experimental autoimmune encephalomyelitis (EAE), a model of multiple sclerosis, diminishes macrophage infiltration and pro-inflammatory gene expression in the diet-induced obesity model, and reduces graft-vs-host disease." (PMID 29374263, 2018).
ovarian carcinoma (2 papers, 2021 to 2025). A malignant neoplasm originating from the surface ovarian epithelium. "Furthermore, CERS6 regulates the calcium pathway and is negatively correlated with disease progression in ovarian cancer." (PMID 41203639, 2025).
squamous cell carcinoma (2 papers, 2020 to 2022). A carcinoma arising from squamous epithelial cells. "In accordance with the mRNA expression data, adeno and squamous cell carcinoma specimens showed obvious CERS6 protein expression, whereas the control tissues did not." (PMID 32902157, 2020).
steatosis (2 papers, 2019 to 2022). Increased lipid within the cytoplasm of cells. "In fact, when CerS6, the enzyme responsible of C14/C16-ceramide synthesis, is downregulated, there is a prevention of steatosis as ceramide also acts as a negative regulator of β-oxidation." (PMID 31861664, 2019). "Inhibition of SPT and CerS (particularly CerS6) presents an attractive target for avoiding MetS-derived steatosis and NASH development." (PMID 31861664, 2019).
atherosclerosis (1 paper, 2023). A disease characterized by the build-up of fatty material and calcium deposition in the arterial wall resulting in partial or complete occlusion of the arterial lumen. "CERS6, in particular, is responsible for the preferential generation of C16 ceramide and has been implicated in atherosclerosis regulation." (PMID 38275624, 2023).
Cerebral ischemia (1 paper, 2023). Restriction of arterial blood supply to the brain associated with insufficient oxygenation to support the metabolic requirements of the tissue. "The accumulation of ceramides induced by SIRT3 is an important cause of cerebral ischemia–reperfusion injury, which is achieved through the activation of deacetylation of CerS1, CerS2, and CerS6 by SIRT3." (PMID 36374406, 2023). "However, an experiment conducted in 2016 showed that SIRT3 is activated by a currently unknown mechanism and increases the deacetylation level and activity of CerS1, CerS2, and CerS6 after cerebral ischemia–reperfusion." (PMID 36374406, 2023).
diabetic kidney disease (1 paper, 2023). Progressive kidney disorder caused by vascular damage to the glomerular capillaries, in patients with diabetes mellitus. "NEW & NOTEWORTHY This article addresses the roles of ceramide synthase 6 (CERS6) and CERS6-derived ceramides in renal tubular epithelial cells of diabetic kidney disease (DKD) associated interstitial fibrosis." (PMID 37458434, 2023). "Taken together, these experiments suggest that down-regulation of Cers6 expression in vivo can reverse the inhibited mitophagy and restore mitochondrial morphology in diabetic kidney disease." (PMID 37458434, 2023). "The results above indicate that Cers6 and Cers6-derived CER were enhanced in diabetic kidney disease." (PMID 37458434, 2023). "Our results illustrated that CERS6-derived ceramide may aggravate interstitial fibrosis in diabetic kidney disease by regulating PINK1-mediated mitophagy." (PMID 37458434, 2023).
esophageal cancer (1 paper, 2025). A primary or metastatic malignant neoplasm involving the esophagus. "Results showed that the mRNA levels of CERS6 were markedly increased in esophageal cancer tissues compared to normal tissues." (PMID 41203639, 2025). "To further confirm whether the mRNA expression of CERS6 is higher in ESCC, we analyzed the mRNA sequencing data from The Cancer Genome Atlas (TCGA) database, which contains 11 normal esophageal and 184 esophageal cancer tissues." (PMID 41203639, 2025).
folate deficiency (1 paper, 2024). A nutritional condition produced by a deficiency of FOLIC ACID in the diet. "Another study showed that CerS6 knockdown with siRNA suppressed mitochondrial apoptosis induced by folate deficiency in vitro." (PMID 38431645, 2024).
glioblastoma (1 paper, 2024). The most malignant astrocytic tumor (WHO grade IV). "Bcl2L13 was shown to be overexpressed in glioblastoma tumors and binds CerS2 and CerS6, which inhibits the de novo synthesis of ceramides." (PMID 38894892, 2024). "IL-24, a cytokine that triggers apoptosis, was reported to stabilize CerS6, inducing ceramide synthesis, reactive oxygen species (ROS) production, and Ca2+ elevation to promote human glioblastoma cell death in response to endoplasmic reticulum (ER) stress." (PMID 38894892, 2024).
glioma (1 paper, 2017). A benign or malignant brain and spinal cord tumor that arises from glial cells (astrocytes, oligodendrocytes, ependymal cells). "Conversely, the mRNA level of CERS6 was significantly decreased in CERS1 overexpressed glioma cells." (PMID 29262618, 2017).
hepatocellular carcinoma (1 paper, 2025). A malignant tumor that arises from hepatocytes. "Notably, CERS5 and CERS6 emerge as actionable enectors of IL-6 associated hepatic dysfunction: higher CERS5/6 expression correlates with reduced survival in hepatocellular carcinoma." (PMID 41256541, 2025).
intracerebral hemorrhage (1 paper, 2025). A cerebrovascular disorder characterized by bleeding into one or both cerebral hemispheres including the basal ganglia and the cerebral cortex. "Also, using other brain damage models, it has been described that intracerebral hemorrhage by hemin treatment increases the upregulation of ceramide synthase 6 (CerS6) and CerS6-derived C16 ceramide biosynthesis." (PMID 40535970, 2025).
invasive breast carcinoma (1 paper, 2024). A carcinoma that infiltrates the breast parenchyma. "Investigators determined the presence of invasive breast carcinoma is negatively associated with CerS6/S1PR2 or CerS6/SphK1 expression." (PMID 38698424, 2024).
lipid metabolism disorders (1 paper, 2025). "Therefore, decreased expression of ApoB48 can ameliorate lipid metabolism disorders induced by an HFD, which may be related to the CerS6/PP2A/AKT pathway." (PMID 41154683, 2025).
lung adenocarcinoma (1 paper, 2016). A carcinoma that arises from the lung and is characterized by the presence of malignant glandular epithelial cells. "Furthermore, the siRNA silencing of CerS6 robustly protected A549 lung adenocarcinoma cells from MTX toxicity, while the silencing of another ceramide synthase, CerS4, which was also responsive to folate stress in our previous study, did not interfere with the MTX effect." (PMID 26783755, 2016).
oral squamous cell carcinoma (1 paper, 2025). "Research has found that upregulating ceramide synthase 6 (CerS6) expression markedly suppresses mitophagy and promotes mitochondrial fission in oral squamous cell carcinoma, thereby inducing apoptosis in resistant cells." (PMID 41573644, 2025).